RN7SL783P (RNA, 7SL, cytoplasmic 783, pseudogene)
Gene: Miscellaneous RNA gene on chromosome 13 (110,097,851 to 110,098,151, reverse strand). Ensembl gene ENSG00000265885.
Homologues: Orthologues: chimpanzee Metazoa_SRP (99% identical), macaque Metazoa_SRP (93% identical). Paralogues in human: RN7SL1 (84% identical), RN7SL2 (84% identical), RN7SL3 (83% identical), RN7SL220P (82% identical), RN7SL630P (81% identical), RN7SL650P (81% identical), RN7SL122P (80% identical), RN7SL126P (80% identical), RN7SL127P (80% identical), RN7SL769P (80% identical), RN7SL814P (80% identical), RN7SL45P (80% identical), and 701 more.